ZNF32 (zinc finger protein 32)
Diseases named in the same sentence as ZNF32 in open-access papers (continued):
Sharing a sentence is not in itself a finding about the gene and the disease.
tumor (7 papers, 2015 to 2025). "Overall, these data indicate that ZNF32 histidine 179 and 183 single-site mutations can promote tumor growth in vivo." (PMID 40046230, 2025). "To verify the consistency of the differential regulation of tumor cell proliferation by ZNF32 histidine 179 and 183 single-site and double-site mutations in vitro and in vivo, we constructed a subcutaneous xenograft tumor model in nude mice." (PMID 40046230, 2025). "The diversity of the tumor microenvironment complicates the analysis of the in vivo mechanisms underlying ZNF32 regulation of tumor growth." (PMID 25786368, 2015). "In contrast, depletion of ZNF32 increases the oxidative damage caused by pro-oxidant agents and enhances tumor suppression both in vitro and in vivo." (PMID 26497555, 2015). "Consistently, we showed that low expression of ZNF32 was significantly associated with the necrosis of tumor areas in clinical HCC samples." (PMID 26497555, 2015). "However, PL treatment caused a remarkable reduction in tumor weight and volume for xenografts derived from ZNF32-silenced cells compared to those from control cells." (PMID 26497555, 2015). "We also evaluated the effects of different ZNF32 mutants on tumor formation and growth processes in mouse models." (PMID 40046230, 2025). "And tumor growth curve further confirmed that overexpression of ZNF32 can increase the tumorigenicity of SW480 and pCRC1." (PMID 35115495, 2022). "The number of cells required to generate at least one tumour sphere/well was determined to be 10.7 in ZNF32 over-expressing cells and 18.3 in vector control cells." (PMID 30478301, 2018). "The ZNF32-over-expression group (ZNF32 shGPER-NC + DMSO) only required 1 × 105 cells to form tumours." (PMID 30478301, 2018). "Interference against GPER expression alone (vector shGPER + DMSO) or knockdown of its expression in ZNF32 over-expressing cells (ZNF32 shGPER + DMSO) delayed tumour formation (compared to vector shGPER-NC + DMSO or ZNF32 shGPER-NC + DMSO groups)." (PMID 30478301, 2018). "We previously found that zinc finger protein 32 (ZNF32), an important transcription factor associated with cancer in Homo sapiens, protects tumor cells against cell death induced by oxidative stress and other stimuli." (PMID 27763636, 2016). "In tumor xenografts, knockdown of ZNF32 markedly increased the potency of the pro-oxidant drug PL, leading to enhanced tumor suppression." (PMID 26497555, 2015). "Compared with the WT group, the tumor volumes in the ZNF32 histidine 179 and 183 single-site mutation groups were significantly higher while no significant change was noted in the ZNF32 H179, 183A group." (PMID 40046230, 2025). "Knockdown of GPER expression (ZNF32 shGPER + DMSO/vector shGPER + DMSO) led to a requirement for high cell numbers for tumour formation, and the tumour incidence was lower with the same cell numbers compared to the control groups (ZNF32 shGPER-NC + DMSO/vector shGPER-NC + DMSO)." (PMID 30478301, 2018). "With the same cell numbers, the ZNF32-over-expression group showed the highest tumour incidence." (PMID 30478301, 2018). "The ZNF32 over-expression group (ZNF32 shGPER-NC + DMSO) showed the earliest tumour formation." (PMID 30478301, 2018). "ZNF32 expression was associated with a 1.97-fold higher risk of death, whereas other parameters (including sex, tumor stage and grade, and Ki67 positivity) were not significantly related to the risk of death." (PMID 27763636, 2016). "Surprisingly, inconsistent with our prediction, we found that ZNF32 knockdown of MCF-7 cells could form tumor masses that were larger in volume and weight in the null mouse models." (PMID 25786368, 2015). "We are further studying the complexity of ZNF32 regulation of tumor growth in vivo." (PMID 25786368, 2015). "Knockdown of ZNF32 slightly accelerated tumor xenograft growth in DMSO-treated control mice." (PMID 26497555, 2015).
tumor (continued). "Future studies aimed at assessing which transcription factor partners with ZNF32 to control mitochondrial metabolism, the antioxidant system and the tumor microenvironment will help us to more precisely elucidate the role of ZNF32 in tumor progression and therapy." (PMID 26497555, 2015). "Interestingly, although unable to directly affect cell viability in vitro, ZNF32 was observed to regulate tumor growth in vivo." (PMID 25786368, 2015). "Moreover, ZNF32 was also shown to be correlated with autophagy in xenograft tumor-loaded mice and cancer patients." (PMID 25786368, 2015). "Next, to determine whether ZNF32 reduces oxidative damage in vivo, the content of 8-hydroxydeoxyguanosine (8-OHdG), a marker of oxidative DNA damage, was determined in the sections of tumor tissue from xenografted animals." (PMID 26497555, 2015). "A correlation between ZNF32/GPER expression and increased tumor incidence and burden was observed in xenograft mouse models." (PMID 30478301, 2018). "Furthermore, we confirmed that knocked out the LEPR gene in SW480-lv-ZNF32 and pCRC1-lv-ZNF32, the CD133 and Ki-67 positive cells were decreased, and the proportion of apoptosis cells was increased in tumor tissues." (PMID 35115495, 2022). "We also evaluated the roles of ZNF32 and GPER in tumour formation." (PMID 30478301, 2018). "The inhibition of both ZNF32 and TGF-βR might augment the anti-tumor effect of chemotherapeutic drugs and improve the in vivo survival time of patients." (PMID 27763636, 2016). "The group with higher ZNF32 expression showed worse outcomes, and other parameters (such as sex, tumor stage and grade, and Ki67 positivity) were found to not affect the risk of death." (PMID 27763636, 2016). "Similarly, the tumor formation rates were higher in the ZNF32 H179A and H183A groups but not significant in the ZNF32 H179, 183A group compared to the WT group." (PMID 40046230, 2025). "Finally, we investigated ZNF32 and LEPR expression in clinical tumor specimens from CRC patients." (PMID 35115495, 2022). "However, ZNF32-enhanced tumor growth was decreased by the application of the TGF-βR inhibitor LY2157299, suggesting that ZNF32 could protect AC cells and maintain their rapid growth in vivo through the TGF-βR pathway in response to anti-tumor drug administration." (PMID 27763636, 2016).
cancer (6 papers, 2015 to 2025). A tumor composed of atypical neoplastic, often pleomorphic cells that invade other tissues. "ZNF32, an important transcription factor of the Krüppel-like protein family that is associated with cancer in Homo sapiens, has recently become a focus of cancer studies." (PMID 27763636, 2016). "Our results in the present study provide another possible explanation that the high expression of ZNF32 in cancer cells facilitates their differentiation toward CSCs, which are known to be drug resistant." (PMID 35115495, 2022). "Based on our previous studies, ZNF32 protects cancer cells against oxidative stress-induced apoptosis by modulating C1QBP transcription." (PMID 30478301, 2018). "For HCC patients with high ZNF32 expression, ZNF32 inhibition combined with agents that induce oxidative stress represent an efficient strategy for killing cancer cells." (PMID 26497555, 2015). "Based on our observations, even though interfering with ZNF32 expression augmented spontaneous autophagy in carcinoma cells, the viability of these cells remained unaffected." (PMID 25786368, 2015). "We examined the autophagic activity and LC3 II expression in human carcinoma cell lines with increased or decreased ZNF32 expression." (PMID 25786368, 2015). "ZNF32 has been shown to be expressed in many cancer cells, including CRC cells." (PMID 35115495, 2022). "We hypothesized that ZNF32-mediated regulation might also be applicable for other cancer stem cells." (PMID 35115495, 2022). "In contrast, ZNF32 knockdown increased the sensitivity of cancer cells to CIS and GEF." (PMID 27763636, 2016). "As growing cancer cells in vivo are typically subjected to mild oxidative stress, including hypoxia and altered metabolism, ZNF32 performs an important function in the protection of cells from oxidative stress-induced apoptosis, and this function enables cell survival and proliferation." (PMID 26497555, 2015). "In ZNF32-defective carcinoma cells, which lack this protective mechanism, ROS may induce a higher level of autophagy and increase cancer cell death." (PMID 25786368, 2015). "Taken together, our data suggest a novel mechanism by which the Sp1-ZNF32-C1QBP axis resists oxidative stress, and we propose that ZNF32 may serve as a therapeutic target to enhance the sensitivity of cancer to pro-oxidant agents." (PMID 26497555, 2015). "Until recently, several lines of evidence have indicated that ZNF32 may be involved in the diverse processes of cancer progression." (PMID 25786368, 2015). "Consequently, we faithfully recognize that a further investigation of ZNF32 functions in cancer biology would stimulate great advances in cancer diagnostics and therapeutics." (PMID 25786368, 2015). "It remains unknown whether human ZNF32 modulates autophagic activity in carcinoma cells and affects cell viability." (PMID 25786368, 2015). "Zinc finger protein 32 (ZNF32) is a confirmed nuclear protein that acts as a transcription factor to regulate the transcription of target genes GPER and C1QBP to affect stem-cell-like characteristics as well as cancer cell apoptosis, respectively." (PMID 40046230, 2025). "ZNF32 overexpression enhanced the tolerance of cancer cells to not only the conventional anti-proliferative drug CIS but also the EGFR inhibitor GEF." (PMID 27763636, 2016).
ZNF32 also shares sentences with these, for which no sentence is quoted: Obesity (2 papers); diabetes (1); sexual disorder (1).